FRA10AC1 (FRA10A associated CGG repeat 1)
Description:
May be involved in pre-mRNA splicing.
Synonyms: C10orf4; F26C11.1-like; FRA10A; NEDGFC
Tractability: PROTAC: ubiquitination databases record sites on it; its protein half-life has been measured.
Gene: Protein-coding gene on chromosome 10 (93,667,883 to 93,703,294, reverse strand). Ensembl gene ENSG00000148690.
Subcellular location: Nucleus
Gene Ontology:
Molecular function: protein binding
Biological process: mRNA splicing, via spliceosome
Cellular component: nucleus
Genetic constraint (gnomAD): Loss-of-function variants: 3 observed, 3.42 expected, observed/expected ratio (o/e) 0.88, 90% interval 0.39 to 1.81. That is too few expected variants to judge how well the gene tolerates losing a copy. Missense variants: 22 observed, 26.94 expected, observed/expected ratio (o/e) 0.82, 90% interval 0.58 to 1.17. Synonymous variants: 13 observed, 8.72 expected, observed/expected ratio (o/e) 1.49, 90% interval 0.94 to 1.92.
Homologues: Orthologues: chimpanzee FRA10AC1 (99% identical), macaque FRA10AC1 (98% identical), dog FRA10AC1 (92% identical), pig FRA10AC1 (91% identical), mouse Fra10ac1 (87% identical), rat Fra10ac1 (84% identical), rabbit FRA10AC1 (68% identical), zebrafish fra10ac1 (66% identical), tropical clawed frog fra10ac1 (63% identical), guinea pig FRA10AC1 (55% identical), Caenorhabditis elegans C08H9.16 (36% identical), Drosophila melanogaster CG16890 (32% identical). Paralogues in human: ACP3 (14% identical), ACP6 (13% identical), ACP2 (12% identical), ACP4 (12% identical), PXYLP1 (11% identical).